CASP1 (caspase 1)
Diseases named in the same sentence as CASP1 in open-access papers (continued):
Sharing a sentence is not in itself a finding about the gene and the disease.
heart disease (5 papers, 2022 to 2025). "Activated caspase-1 catalyzes the processing of interleukin-1β and interleukin-18 precursors into their active forms to stimulate the inflammatory response in heart diseases." (PMID 40149903, 2025). "In contrast to prematurity-induced cardiac remodeling, several studies have investigated the role of caspase-1 in adult cardiac disease." (PMID 41231039, 2025). "The expressions of pyroptosis-related NLRP3, GSDMD, caspase-1, IL-1β, and IL-18 in these heart disease patients were elevated." (PMID 35647057, 2022). "In addition, the NLRP3/Caspase-1/IL-1β pathway is present in the inflammatory response in heart disease." (PMID 39640484, 2024).
respiratory diseases (4 papers, 2015 to 2024). "In summary, targeting the NLRP3 inflammasome is a viable strategy for inhibiting pyroptosis and treating respiratory diseases, whereas other targets, such as caspase-1, also exhibit therapeutic potential." (PMID 39300122, 2024). "Among the traditional signaling pathways, NLRP3 and caspase-1 play the most extensive role in respiratory diseases." (PMID 36248872, 2022). "Recently, several studies explored the functions of caspase-1 in respiratory diseases." (PMID 26496436, 2015).
adenocarcinoma (3 papers, 2002 to 2024). A common cancer characterized by the presence of malignant glandular cells. "In the case of the pancreas, it has been suggested that expression of caspase-1 is elevated in adenocarcinoma as compared to normal pancreas tissue." (PMID 11953820, 2002). "In addition, studies have shown that the overexpression of miR-223 in human adenocarcinoma alveolar basal epithelial cells can reduce LPS-induced Caspase-1, IL-1β, and IL-18 levels by targeting NLRP3." (PMID 38448875, 2024).
central nervous system diseases (3 papers, 2015 to 2023). "VX-765 is a potent small-molecule caspase-1 inhibitor that protects against central nervous system diseases." (PMID 36441377, 2022).
hematologic disorder (2 papers, 2022 to 2025). A disease involving the hematopoietic system. "This study demonstrates the efficacy of integrating traditional statistical methods, ML, and XAI to unravel the complex gene interactions in hematological malignancies, with a specific focus on the NF-κB1 and caspase-1 axis." (PMID 40303498, 2025).
retinopathy (2 papers, 2016 to 2024). "We further found an increased co-location of NLRP3, Iba-1, and IL-1β in fluorescence and a concomitant increased protein expression of NLRP3, caspase-1, and IL-1β in western blotting in chronic blue light-induced retinopathy." (PMID 27831552, 2016).
vascular disorder (2 papers, 2017 to 2024). A general term used to describe any disease affecting blood vessels]. "Complexes such as Bcl3/NF-kappaB2 complex (governed by BCL3 and NFKB2), vacuolar lumen (governed by CLN5), IPAF inflammasome complex (CASP1, CASP4, NLRC4) help to understand the involvement of inflammation and vascular disorder in AD." (PMID 28199395, 2017).
head and neck tumors (1 paper, 2024). "In this study, it was found that IL-1α, IL-1β, IL1R1, IL1RL1, IL1F10, IL33, CASP1, and AIM2 were highly expressed in head and neck tumors, while IL1RN, IL1RAPL1, IL1RAPL2, IL18BP, IL18R1, and IL18RAP were low in expressed, which is consistent with previous literature." (PMID 39461030, 2024).
CASP1 also shares sentences with these, for which no sentence is quoted: acute myocardial infarction (6 papers); cognitive disorder (5); Encephalopathy (5); Parkinson (5); brain disease (4); liver cancer (4); prostatitis (4); airway hyperresponsiveness (3); idiopathic pulmonary fibrosis (3); inflammatory skin disease (3); metastatic melanoma (3); Retinal atrophy (3); alcoholic hepatitis (2); candidiasis (2); Chagas disease (2); Chlamydia infection (2); dilated cardiomyopathy (2); gingivitis (2); Infertility (2); laryngeal squamous cell carcinoma (2); Legionella pneumonia (2); lymphopenia (2); myelodysplastic syndrome (2); non-Hodgkin lymphoma (2); oral lichen planus (2); pancreatic ductal adenocarcinoma (2); respiratory infection (2); retinitis (2); skin infection (2); ventricular dilatation (2).
A further 135 diseases each share a sentence with CASP1 in 2 papers or fewer.